CPT1A (carnitine palmitoyltransferase 1A)
Diseases named in the same sentence as CPT1A in open-access papers (continued):
Sharing a sentence is not in itself a finding about the gene and the disease.
tumor (continued). "However, the underlying molecular mechanism of how CPT1A confers PCa tumor aggressiveness, particularly under hypoxic conditions, is still to be determined." (PMID 34944922, 2021). "Similarly, CPT1A expression was closely associated with tumor stage." (PMID 40016582, 2025). "In addition, there is growing evidence that CPT1A expression is closely linked to tumor immunity." (PMID 39596847, 2024). "Interestingly, CPT1a expression is mostly localized around tumor-associated adipocytes." (PMID 35158830, 2022). "Furthermore, three-dimensional culture studies showed that CPT1A is upregulated in tumor cells within adipose tissues compared to that not in direct contact with adipocytes, whereas CPT1A silencing reduces tumor organoid formation and downregulates genes associated with cancer stem cells." (PMID 34764874, 2021). "Moreover, CPT1C may be a key element of mitochondrial dysfunction-associated tumor cellular proliferation and senescence and functionally differs from the other three subtypes CPT1A, CPT1B and CPT2 11,12." (PMID 32641987, 2020). "Finally, analysis of lipid storage markers showed an increased expression of perilipin 2 (PLIN2) and hypoxia inducible lipid droplet-associated (HILPDA), and reduced levels of carnitine palmitoyltransferase 1A (CPT1A) mRNA in tumor specimens compared to normal kidney." (PMID 33322148, 2020). "Here we identified the tumor specific nuclear CPT1A as a product of the transcript variant 2, that doesn't retain the classical transferase activity and is strongly involved in the epigenetic regulation of cancer pro-survival, cell death escaping and tumor invasion pathways." (PMID 26799588, 2016). "Inhibition of CPT1A impairs anchorage-independent tumor growth and reduces NADPH supply, disrupting tumor cell survival." (PMID 41476608, 2025). "These dormant disseminated tumor cells (DTCs) often shift their metabolism towards FAO mediated by the enzyme carnitine palmitoyl-transferase 1A (CPT-1A)." (PMID 41488002, 2025). "CPT1A-mediated ROS elimination can also sometimes increase metastatic ability by inhibiting tumor anoikis." (PMID 41219902, 2025). "Several studies have shown that CPT1A-driven fatty acid beta-oxidation can facilitate cancer cell proliferation and survival, as well as tumor invasion." (PMID 41154660, 2025). "H&E staining revealed that there was more tumor cells necrosis in sh-RACGAP1 group, and CPT1A overexpression weakened such necrosis caused by RACGAP1 silencing." (PMID 41444950, 2025). "CPT1A is often overexpressed in different types of tumors and contributes to tumor metastasis, prevents apoptosis, and aids in resistance to radiotherapy and chemotherapy by enabling FAO." (PMID 41293266, 2025). "Succinyltransferase inhibitors (CPT1A inhibitors) developed for this pathway can be combined with surgery to block ECM remodeling and reduce the risk of tumor cells shedding and metastasis during surgery." (PMID 40865948, 2025). "Single-cell RNA sequencing of intratumoral immune cells has revealed that this diet induces RUNX3 acetylation, inactivating CPT1A, reducing B cell to IgA conversion, and promoting tumor regression." (PMID 41219902, 2025). "A previous study demonstrated that simultaneously targeting sterol O-acyltransferase 1 and CPT1A effectively suppressed tumor growth both in vitro and in vivo." (PMID 39708716, 2025). "This process is regulated by carnitine palmitoyltransferase-1A (CPT1A), driving ATP production to fuel tumor cell metabolism and proliferation." (PMID 40852589, 2025). "Mechanistically, CPT1A inhibition enhances tumor ferroptosis, promoting the infiltration and activation of CD8+ T cells within the tumor microenvironment." (PMID 40867868, 2025). "Further supporting our observations, immunofluorescence staining, ATP production, and western blot assays conducted on the extracted tumor masses revealed that miR-365-3p significantly suppressed FAO by regulating CPT1A." (PMID 40016582, 2025).
tumor (continued). "The overexpression of CPT1A in GC tissues and its elevated levels in patient serum underscore its pivotal role in tumour metabolism and progression." (PMID 41154605, 2025). "For instance, adipocytes serve as a lipid source, enhancing the expression of CD36, CPT1A/B, FATPs, and FABPs in tumor cells, thereby promoting FAO, which in turn supports tumor cell proliferation and invasive capabilities." (PMID 40616161, 2025). "The genetic and pharmacological inhibition of CPT1A function significantly suppressed the metastatic colonization of CCa cells in tumor-draining lymph nodes." (PMID 40641601, 2025). "CPT1A was thought to play a crucial role in this metabolic paradigm shift, and CPT1A-mediated fatty acid oxidation has been proved to be conducive to tumor metastasis, radiation resistance, and immune escape." (PMID 40658605, 2025). "ANXA2 supports angiogenesis in specific tumor-related settings, and its expression level was positively correlated with that of Cpt1a in S100a4+ alv-macro." (PMID 40658605, 2025). "Consistent with the results in vitro, the overexpression of miR-365-3p or knockdown of CPT1A effectively suppressed tumor growth." (PMID 40016582, 2025). "IHC analyses have demonstrated higher CPT1A levels in tumours with distant metastasis and Helicobacter pylori positivity." (PMID 41154605, 2025). "Secondly, SLC6A19 plays a significant role in ccRCC and presents intimately correlation with fatty acid metabolism alongside with CPT1A, which is extensively considered as a tumor suppressor of ccRCC." (PMID 40099255, 2025). "Research has established that the expression of CPT1A is significantly downregulated in ccRCC tumor tissues and patients exhibiting reduced CPT1A levels were frequently correlated with a poorer OS." (PMID 40099255, 2025). "H&E staining and immunohistochemical analysis further confirmed that FATP4 and CPT1A promoted tumor growth in vivo, consistent with the molecular biology results." (PMID 41310903, 2025). "Then we aimed to figure out the contribution of Cpt1a to angiogenesis and pro-tumor function in S100a4+ alv-macro." (PMID 40658605, 2025). "CPT1A-stabilising knockout increased tumour weights in mice, which persisted after radiotherapy, suggesting that CPT1A knockout promotes tumour growth and confers increased resistance to radiation." (PMID 39607749, 2024). "Further characterization in genetic mouse and tumor models is needed to understand the role of CPT1A-mediated FAO in the CD8+ T-cell-regulated antitumor response." (PMID 39402302, 2024). "The results revealed that the carcinogenic effect of Cori.ST1911 was reversed when combined with etomoxir, which suggest that Cori.ST1911 promotes tumour development by upregulating CPT1A expression." (PMID 38245554, 2024). "Using an ErbB2+ Genetically Engineered Mouse Model (GEMM), we show that Cpt1a ablation delays tumor onset in ErbB2+ tumors, reducing both angiogenesis and metastatic capacity." (PMID 39097623, 2024). "CPT1A overexpression resulted in reduced tumour weight in mice, a trend that persisted even after radiotherapy." (PMID 39607749, 2024). "Previous data emphasized the significance of CPT1A in cancer cell proliferation, metastasis, and induced tumor senescence via FAO regulation." (PMID 39456670, 2024). "Previous research, combined with our findings, emphasizes the role of Cpt1a in shaping the immune landscape within tumor lesions." (PMID 39097623, 2024). "Correlation between clinicopathological features and the expression of CPT1A in tumour paraffin section." (PMID 39607749, 2024). "IHC staining demonstrated a significant increase in Ki-67 staining intensity and the percentage of positive cells in CPT1A knockout tumours, indicating enhanced proliferative capacity that was further pronounced after radiotherapy." (PMID 39607749, 2024). "Bioinformatic analysis and tumour tissue examination were conducted to investigate the CPT1A mRNA and protein levels in CRC and their correlation with radiotherapy efficacy." (PMID 39607749, 2024).
tumor (continued). "The HIF-2α/CPT1A lipid storage axis can inhibit fatty acid transport into mitochondria to promote lipid droplet formation and tumor growth." (PMID 38649345, 2024). "Downregulation of the CPT1A gene can lead to a defective lipid transport system to promote lipid deposition and tumor growth, and CPT1A has been shown to be a direct target gene of HIF-2α." (PMID 38649345, 2024). "Since complete ablation of Cpt1a reduced tumor focality and proliferative capacity, we examined lung metastasis in mice with equivalent tumor volume to control for potential confounding effects." (PMID 39097623, 2024). "Meanwhile, CPT1A protein levels were lower in most CRC tissues (14/16 pairs) than in the adjacent non-tumour tissues." (PMID 39607749, 2024). "Immunohistochemistry (IHC) staining of the cancer-adjacent borders of two patients showed that CPT1A protein levels were lower in CRC tissues than in the nearby non-tumour tissues." (PMID 39607749, 2024). "It has been reported that CPT1A pumps fatty acids into mitochondria to consume LDs in ccRCC, leading to tumor growth restriction." (PMID 39600540, 2024). "LncRNA NEAT1 negatively regulated miR-107, promoting CPT1A expression and facilitating β-oxidation, ultimately contributing to tumor progression." (PMID 38408962, 2024). "Significantly, targeting CPT1A enhances immune checkpoint blockade-induced anti-tumor immunity and tumoral ferroptosis in tumor-bearing mice." (PMID 38453925, 2024). "In contrast, combining Cpt1a ablation with the ketogenic diet markedly decreased tumor growth and enhanced survival compared to all other conditions." (PMID 39097623, 2024). "Taken together, our findings suggest that Cpt1a inhibition can significantly inhibit tumor growth, promote apoptosis, and reduce the occurrence of lung metastases when combined with a ketogenic diet or HER2 monoclonal antibody therapy." (PMID 39097623, 2024). "Here, we demonstrate that combining Cpt1a inhibition with either the ketogenic diet, rich in LCFAs, or an anti-ErbB2 mAb reduces tumor growth, prolongs survival and enhances anti-tumor immune infiltration." (PMID 39097623, 2024). "Glucose deficiency and metabolic stress promote both an increase in carnitine palmitoyl transferase 1 A (CPT1A) protein levels and an increase in CPT1C expression in the tumor tissues of patients with PTC compared to adjacent normal tissues." (PMID 39000236, 2024). "IHC staining for Ki-67 revealed significantly decreased staining intensity and percentage of positive cells in CPT1A-overexpressing tumours, indicating weakened proliferative capacity, which was further accentuated after radiotherapy." (PMID 39607749, 2024). "CPT1A, a rate-limiting enzyme in fatty acid oxidation, undergoes upregulation in various tumor types." (PMID 38693136, 2024). "Increased CPT1A expression promotes tumor progression and metastasis by inhibiting cell death (apoptosis) or detachment-induced cell death (anoikis) in breast cancer and leukemia." (PMID 39456967, 2024). "Modified iRGD exosomes demonstrated significant inhibition of CPT1A in tumor tissues and showed the ability to reverse oxaliplatin resistance and inhibit tumor growth by inhibiting fatty acid oxidation in vivo." (PMID 39594723, 2024). "As a key rate-limiting enzyme in mitochondrial long-chain free fatty acid uptake for beta-oxidation (FAO), CPT1A plays an important role in tumor progression, epithelial-mesenchymal transition (EMT) and migration." (PMID 37291333, 2023). "The inhibitors of CPT1A, etomoxir and perhexiline, were applied to enhance carboplatin sensitivity, which reduced tumor growth in vivo significantly when combined with carboplatin." (PMID 38003694, 2023). "In preclinical models, the inhibition of FAO by etomoxir, a drug that targets the rate-limiting enzyme carnitine palmitoyl-transferase 1a (CPT1a), led to a reduction in tumor growth." (PMID 37251409, 2023).
tumor (continued). "For instance, inhibition of FAO by etomoxir, a specific inhibitor of CPT1A, blocks the immune-suppressive abilities of tumor-infiltrating MDSCs, resulting in T-cell-dependent tumor growth restriction." (PMID 37469520, 2023). "The main drawback of CPT1A blockage is the undesirable impact on non-tumor cells given the extensive tissue distribution of CPT1A." (PMID 37033619, 2023). "One indicator of RT and CT resistant tumor cells is thought to be the abnormal upregulation of CPT1A-dependent FAO." (PMID 37033619, 2023). "In particular, we found that carnitine and short-chain acylcarnitines were reduced in concentration in HB and that the carnitine metabolic pathway was dysregulated in the tumours (CPT1a, CPT2 and SLC25A20)." (PMID 37958356, 2023). "Corroboratively, IHC showed lower expression of CPT1a in tumour, showing downregulation of the carnitine cycle at both RNA and protein levels." (PMID 37958356, 2023). "Based on the strong tumour-promoting effect of CPT1A, inhibitors and antagonists designed against CPT1A are potential anti-tumour strategies." (PMID 37416765, 2023). "High expression of CPT1A not only enhances radiotherapy resistance in GBM tumor cells, but also enhances immune escape of macrophages through CD47, suggesting CPT1A as a novel strategy for the treatment of recurrent GBM multiforme." (PMID 37033619, 2023). "CPT1A mediates FAO to promote tumor cell proliferation and identify fatty acids as providing a carbon source for the synthesis of nucleoside metabolic intermediates by metabolic flux analysis." (PMID 35411000, 2022). "Altogether, these results indicate that STAT3 signaling induces CPT1A expression, which in turn protects Tc9 cells from ROS- or tumor-induced ferroptosis." (PMID 35192544, 2022). "Overexpression of CPT1A has been reported in other cancer types and normal cells to promote tumor growth and cell proliferation." (PMID 35223522, 2022). "GBM tissues exhibited overexpression of FAO-related genes, especially CPT1A, compared to the tumor-free cortex." (PMID 36221088, 2022). "In this case, STAT3, the transcription activator of CPT1a, attenuates the tumoricidal function of Teff cells and promotes tumor progression." (PMID 39872079, 2022). "For the fatty acid transporters, there was no variation in the expression of CD36 between groups, albeit lower in PY8119 tumors, while CPT1a expression was significantly increased in tumors from HFD-fed mice for both tumor models." (PMID 35158830, 2022). "For instance, CPT1A was found upregulated in hormone receptor-positive BC and plays a key role in cell proliferation and drug resistance in this tumor type." (PMID 36551752, 2022). "Pharmacological inhibition of CPT1A with etomoxir was mostly used in research, but some experiments also indicated promising anti-tumor results." (PMID 35392503, 2022). "Further studies are needed to probe the mechanistic role CPT-1A plays in determining the balance of pro- and anti-tumour immune activity in the tumour microenvironment." (PMID 36180554, 2022). "We also demonstrated that tumor cells with CPT1A downregulation induced by CAFsCPT1A‐OE increased tumor growth and invasion by increasing glycolysis." (PMID 33528867, 2021). "Carnitine palmitoyl transferase 1A (CPT1A), the key regulator of fatty acid oxidation, contributes to tumor metastasis and therapeutic resistance." (PMID 33858374, 2021). "CAFsCPT1A‐OE significantly decreased the level of CPT1A in tumor cells; in contrast, the expression of CPT1A in CRC cells can be upregulated by vector control CAFs." (PMID 33528867, 2021). "Our results showed that expression of CPT1A or SIRT5 was negatively correlated with deeper tumor infiltration and distant metastasis, whereas the expression of SIRT7 exhibited opposite effect." (PMID 33681201, 2021).
tumor (continued). "As a consequence, iRGD‐modified exosomes showed the significant inhibition of CPT1A in tumour tissues and exhibited the ability to reverse oxaliplatin resistance and inhibit tumour growth by inhibiting FAO with high safety in vivo." (PMID 34213835, 2021). "The results of immunohistochemistry further demonstrated that the expression of CPT1A in tumor sites from PM‐CRC was lower compared with those from non‐PM‐CRC patients." (PMID 33528867, 2021). "As expected, we observed a decrease of fatty acid like tetracosanoic acid in CPT1a high expression group comparing to low expression group, which confirms that CPT1a can facilitate FAO to provide energy fueling tumor growth." (PMID 33926484, 2021). "To assess the effects of CPT1A KD or OE on tumor development in an immunocompromised mouse model, we injected these 22Rv1 cells with stable CPT1A KD or OE as well as respective vector control cells in male nude mice and monitored their growth." (PMID 34944922, 2021). "miR-124 is a tumor suppressor and modulator of carnitine palmitoyltransferase 1A (CPT1A), a key enzyme of mitochondrial fatty acid oxidation which is important for cancer survival and activation of oncogenic pathways." (PMID 34503302, 2021). "Studies have indicated that higher expression or activity of CPT1A plays a role in PCa tumor aggressiveness and chemoresistance." (PMID 34944922, 2021). "We also characterized the effects of CPT1A OE on proliferation-, angiogenesis-, and lymphangiogenesis-related biomarkers in tumor tissues." (PMID 34944922, 2021). "In nude mice, 22Rv1 xenografts with CPT1A knockdown grew significantly slower compared to vector control cells (~59% reduction in tumor volume at day 29)." (PMID 34944922, 2021). "We observed a significant decrease in tumor weight in animals injected with CPT1A KD 22Rv1 cells compared to vector control cells (p < 0.05)." (PMID 34944922, 2021). "In these tissue samples (n = 13), only four genes ID4, HMGCR, ROCK1, and CPT1A were differentially expressed (unadjusted p < 0.01), and no gene expression signatures were significantly different between primary tumor and baseline metastasis samples." (PMID 33428680, 2021). "Since hypoxia in primary tumors invariably affects angiogenesis and lymphangiogenesis, we next characterized the effects of CPT1A KD on proliferation-, angiogenesis-, and lymphangiogenesis-related biomarkers in tumor tissues." (PMID 34944922, 2021). "It has been reported that PAX3‐FKHR (PAX3‐FOXO1), a fusion gene characteristic of ARMS, is involved in the transcription of CPT1A and regulates tumor cell infiltration and metastasis." (PMID 34472721, 2021). "CPT1A upregulation induced metabolic changes, promoted β-catenin acetylation and activated the tumor microenvironment rich in adipocytes." (PMID 34200820, 2021). "On the contrary, CPT1A-overexpressing 22Rv1 xenografts showed higher tumor growth compared to vector control cells (~58% higher tumor volume at day 40)." (PMID 34944922, 2021). "Overall, these results suggest that the status of CPT1A expression can affect 22Rv1 tumor development, as evidenced by the limited growth in tumors with CPT1A KD and enhanced growth in tumors with CPT1A OE." (PMID 34944922, 2021). "Our results also showed that mice injected with 22Rv1 cells with CPT1A KD throughout exhibited slower tumor growth compared to mice injected with vector control cells." (PMID 34944922, 2021). "On the other hand, animals injected with 22Rv1 cells with CPT1A OE showed an increase in tumor volume compared to animals injected with vector control cells." (PMID 34944922, 2021). "Our study showed, on the one hand, that the low level of CPT1A in CRC tumors with PM becomes more favorable to increase tumor growth and invasion by increasing glycolysis." (PMID 33528867, 2021). "The results showed that CPT1A expression in PCa cells is key to their survival and proliferation in the hypoxic tumor microenvironment." (PMID 34944922, 2021).